AHSA1 (activator of HSP90 ATPase activity 1)
Description:
Acts as a co-chaperone of HSP90AA1. Activates the ATPase activity of HSP90AA1 leading to increase in its chaperone activity. Competes with the inhibitory co-chaperone FNIP1 for binding to HSP90AA1, thereby providing a reciprocal regulatory mechanism for chaperoning of client proteins. Competes with the inhibitory co-chaperone TSC1 for binding to HSP90AA1, thereby providing a reciprocal regulatory mechanism for chaperoning of client proteins.
Synonyms: AHA1; C14orf3; p38; hAha1
Tractability: PROTAC: UniProt records ubiquitination sites on it; ubiquitination databases record sites on it; its protein half-life has been measured.
Gene: Protein-coding gene on chromosome 14 (77,457,743 to 77,469,482, forward strand). Ensembl gene ENSG00000100591.
Subcellular location: Cytoplasm, cytosol; Endoplasmic reticulum
Subcellular location (Human Protein Atlas): Cytosol
Gene Ontology:
Molecular function: ATPase activator activity; cadherin binding; Hsp90 protein binding; protein binding; protein folding chaperone; protein-folding chaperone binding
Biological process: positive regulation of ATP-dependent activity; protein folding
Cellular component: cytosol; endoplasmic reticulum; extracellular exosome
Genetic constraint (gnomAD): Loss-of-function variants: 12 observed, 38.49 expected, observed/expected ratio (o/e) 0.31, 90% interval 0.2 to 0.5. The upper end of that interval is the gene's LOEUF score, 0.5, which puts it in group 2 of 6, group 1 being the genes least tolerant of losing a copy. Missense variants: 297 observed, 357.91 expected, observed/expected ratio (o/e) 0.83, 90% interval 0.75 to 0.91. Synonymous variants: 128 observed, 128.85 expected, observed/expected ratio (o/e) 0.99, 90% interval 0.86 to 1.15.
Homologues: Orthologues: chimpanzee AHSA1 (99% identical), macaque AHSA1 (99% identical), dog AHSA1 (97% identical), pig AHSA1 (96% identical), guinea pig AHSA1 (96% identical), mouse Ahsa1 (95% identical), rat Ahsa1 (95% identical), tropical clawed frog ahsa1 (69% identical), zebrafish ahsa1b (64% identical), zebrafish ahsa1a (53% identical), Drosophila melanogaster CG1416 (43% identical), Caenorhabditis elegans ahsa-1 (37% identical).
Diseases named in the same sentence as AHSA1 in open-access papers:
AHSA1 is named in the same sentence as 25 diseases in open-access papers, as found by Europe PMC text mining. Sharing a sentence is not in itself a finding about the gene and the disease. The quoted sentences say what the papers report.
osteosarcoma (6 papers, 2018 to 2022). A usually aggressive malignant bone-forming mesenchymal neoplasm, predominantly affecting adolescents and young adults. "AHSA1 overexpression promoted cell growth, migration, and invasion in osteosarcoma cells by activating the Wnt/β-catenin signaling pathway." (PMID 34316513, 2021). "AHSA1 has been reported to regulate proliferation, apoptosis, migration, and invasion of osteosarcoma." (PMID 32153556, 2020). "Silencing of AHSA1 via siRNA significantly reduced migration of osteosarcoma cells in culture." (PMID 32153556, 2020). "In osteosarcoma, LINC00707 binds to miR-338-3p and increases AHSA1 expression to promote cell migration and invasion." (PMID 35155429, 2022). "The activator of 90 kDa HSP ATPase homolog 1 (AHSA1) is an important chaperone of HSP90, which regulates osteosarcoma invasion." (PMID 36050408, 2022). "In conclusion, we demonstrated high expression of LINC00707 in osteosarcoma cell lines and that silencing LINC00707 suppresses cell proliferation, migration, and invasion by targeting the miR-338-3p/AHSA1 axis in MG-63 and Saos-2 cells." (PMID 34316513, 2021). "Our previous study has demonstrated that miR-338-3p can target-inhibit the expression of AHSA1 to inhibit proliferation, migration, invasion, and EMT in osteosarcoma cells." (PMID 34316513, 2021). "In conclusion, we demonstrated that LINC00707 is highly expressed in osteosarcoma cell lines, and silencing of LINC00707 suppresses cell proliferation, migration, and invasion by targeting the miR-338-3p/AHSA1 axis in MG-63 and Saos-2 cells." (PMID 34316513, 2021). "AHSA1 is a co-chaperone of HSP90AA1, and a previous study has revealed that it is involved in the proliferation, migration, and invasion processes of osteosarcoma." (PMID 31987030, 2020). "Experiments on osteosarcoma MG-63 and Saos-2 cells revealed that LINC00707 exploits positive regulatory effects on cell proliferation by acting as a competing endogenous RNA (ceRNA) of miR-338-3p and further heightening AHSA1 expression." (PMID 35155429, 2022).
hepatocellular carcinoma (3 papers, 2022 to 2024). A malignant tumor that arises from hepatocytes. "Subsequently, the association between AHSA1 expression and clinical stage was analyzed in hepatocellular carcinoma." (PMID 35757728, 2022). "In this study, we found AHSA1 was upregulated and associated with poor clinical characteristics and prognosis of hepatocellular carcinoma patients." (PMID 36230524, 2022). "Subsequently, the protein expression level of AHSA1 were observed in hepatocellular tissues by immunohistochemistry, and according to the findings of this analysis, the level of protein expression of AHSA1 was greater in hepatocellular carcinoma tissues." (PMID 35757728, 2022). "The current research highlighted that the abnormal expression of AHSA1 was closely related to the prognosis of patients with hepatocellular carcinoma." (PMID 35757728, 2022). "The findings of this study suggests that AHSA1 may perform a key role in the development of hepatocellular carcinoma." (PMID 35757728, 2022). "Although the previous findings indicated that AHSA1 was significantly over-expressed in hepatocellular carcinoma and patients with overexpression had poorer survival expectations, the role of AHSA1 in the occurrence of hepatocellular carcinoma needs further study." (PMID 35757728, 2022). "The results of this study are helpful to understand the similarities and differences of AHSA1 expression in a variety of tumors, reveal the potential mechanism of the interaction between AHSA1 and tumor immunity, and demonstrate the potential function of AHSA1 in hepatocellular carcinoma." (PMID 35757728, 2022). "Therefore, further analysis of the association between the expression of AHSA1 and the clinicopathological stage was carried out, and to facilitate the application of AHSA1 in the prognosis assessment of hepatocellular carcinoma, a nomography was constructed." (PMID 35757728, 2022). "Moreover, knockdown of AHSA1 can affect the proliferation and transformation of hepatocellular carcinoma cells." (PMID 35757728, 2022). "Moreover, AHSA1 promoted proliferation, metastasis, epithelium-mesenchymal transition of hepatocellular carcinoma both in vitro and in vivo by recruiting ERK1/2 and promoting the phosphorylation and inactivation of CALD1." (PMID 36230524, 2022). "Results showed higher mRNA expression levels of AHSA1 in hepatocellular carcinoma cells." (PMID 35757728, 2022). "However, the biological function and regulatory mechanism of AHSA1 in hepatocellular carcinoma were unclearly." (PMID 36230524, 2022). "Taken together, our findings provided a mechanistic insight into the role of AHSA1 in hepatocellular carcinoma progression and implied AHSA1 may be a biomarker and therapeutic target for hepatocellular carcinoma patients." (PMID 36230524, 2022). "In addition, this study verified the expression and prognostic role of AHSA1 in hepatocellular carcinoma by combining data from ICGC-LIRI-JP, and verified the expression and potential function of AHSA1 in hepatocellular carcinoma by combining cell and tissue specimens." (PMID 35757728, 2022). "We further evaluated the prognostic role of AHSA1 in hepatocellular carcinoma by univariate and multivariate COX regression combined with clinical data, and the results showed that AHSA1 was an independent prognostic factor of hepatocellular carcinoma." (PMID 35757728, 2022). "For additional verification of the expression of AHSA1 in hepatocellular carcinoma, RT-PCR was performed to detect the mRNA expression levels of AHSA1 in normal hepatocyte cell line LO2 along with three hepatocellular carcinoma cell lines, HCCLM3, HepG2 and Huh7." (PMID 35757728, 2022). "Furthermore, we examined the effect of AHSA1 knockdown on cell function in Huh7 and HCCLM3 cells of hepatocellular carcinoma (HCC) cell lines." (PMID 35757728, 2022).
lung adenocarcinoma (3 papers, 2022 to 2025). A carcinoma that arises from the lung and is characterized by the presence of malignant glandular epithelial cells. "Moreover, analysis of 33 tumors via the cancer genome atlas revealed AHSA1, the gene encoding Aha1, RNA expression was elevated in breast invasive carcinoma, colon adenocarcinoma, lung adenocarcinoma, cholangiocarcinoma and prostate adenocarcinoma." (PMID 39776493, 2024).
breast carcinoma (2 papers, 2010 to 2022). "Previous studies have shown that AHSA1 inhibition can significantly inhibit the proliferation and viability of breast cancer cells." (PMID 35757728, 2022). "In addition, consistently up or down-regulated HSP90 client transcripts following treatment were identified shared by some of the cell lines analyzed (AHSA1, CCNB1, IRAK1), that could represent important HSP90 clients in breast cancer." (PMID 20920318, 2010).
cystic fibrosis (2 papers, 2013 to 2015). Autosomal recessive disorder caused by pathogenic variants in the CFTR gene (cystic fibrosis transmembrane conductance regulator), which encodes a chloride and bicarbonate channel expressed in epithelial cells, and follow the diagnosis criteria. "In 2006, Wang and colleagues observed that the down-regulation of human Hsp90 cochaperone AHA1 (AHSA1) rescues misfolding of CFTR protein in Cystic fibrosis." (PMID 26046679, 2015). "Although HSP90 seems to function predominantly by stabilizing proteins, in cystic fibrosis Ahsa1 downregulation enhances CFTR activity." (PMID 23720234, 2013). "Although most evidence points to Hsp90 buffering against severe phenotypes, evidence in cystic fibrosis suggests that AHSA1-mediated HSP90 activation might correlate with a poorer prognosis." (PMID 23720234, 2013).
multiple myeloma (2 papers, 2022). "We demonstrate that AHSA1 may serve as a promising therapeutic target for cellular proliferation and proteasome inhibitor resistance in multiple myeloma." (PMID 34991674, 2022). "AHSA1 is a therapeutic target for the treatment of multiple myeloma." (PMID 35253368, 2022).
prostate carcinoma (2 papers, 2015 to 2022). A carcinoma that arises from epithelial cells of the prostate gland. "It acts as a regulator of HSP90, and its activation by AHSA1 influences the metabolism of androgen in prostate cancer." (PMID 35625354, 2022). "There were no previous descriptions for the fusions NAIP:OCLN, PDE1C:DNAJC6, KANSL1:ARL17B, FOXP2:CREM, and AHSA1:DLG3 in the context of prostate cancer." (PMID 35625354, 2022).
germ cell tumor (1 paper, 2022). A benign or malignant, gonadal or extragonadal neoplasm that originates from germ cells. "The results showed that AHSA1 was expressed at a relatively low level in normal bile duct tissue and a relatively high level in testicular germ cell tumor tissue." (PMID 35757728, 2022).
liver cancer (1 paper, 2024). An epithelial or non-epithelial malignant neoplasm that arises from the liver. "CALD1 acts as a downstream target of AHSA1, promoting proliferation and EMT in liver cancer." (PMID 38717641, 2024).
melanoma (1 paper, 2023). A malignant, usually aggressive tumor composed of atypical, neoplastic melanocytes. "Under standard conditions (37 °C), melanoma cells were characterized by a high level (>0.04) of HSPD1 (HSP60), HSPA8 (HSP70), and HSP90AB1 (HSP90), and a medium level (0.02–0.04) of HSPB1 (HSP27), HSPA9 (HSP70), and AHSA1 (HSP90)." (PMID 37886980, 2023).
pulmonary fibrosis (1 paper, 2022). Chronic progressive interstitial lung disorder characterized by the replacement of the lung tissue by connective tissue, leading to progressive dyspnea, respiratory failure, or right heart failure. "By analyzing the target interaction network VCAM1,RELA,CDK2,JUN,CDK1,HSP90AA1,NOS2, SOD1,CASP3,AHSA1, PTGER3 are at the core of the network, which can be regarded as the key targets of Astragalus polysaccharides in treating pulmonary fibrosis." (PMID 35370663, 2022).
tumor (8 papers, 2015 to 2025). "Meanwhile, as per the correlation analysis the expression of AHSA1 was greatly correlated with the expression of various immune cell infiltrates, immune checkpoint inhibitors, tumor mutation load, and microsatellite instability." (PMID 35757728, 2022). "Meanwhile, combined with correlation analysis, the possible association between AHSA1 expression and tumor immune cell infiltration, tumor mutation load (TMB), microsatellite instability (MSI) and various pathway-related molecules were explored." (PMID 35757728, 2022). "In NSCLC, miR-338-3p induces anti-proliferative activity by binding to the 3’UTR of multiple genes including AHSA1, where it acts as a tumor suppressor by preventing Aha1 protein expression." (PMID 39776493, 2024). "All experimental investigations demonstrated that AHSA1 was a tumor-promoting oncogene in tumor development and progression and acted as a pro-oncogenic regulator in LUAD." (PMID 37033259, 2023). "AHSA1 is abnormally upregulated in different tumor tissues, and its anomalous expression is related to the prognosis of tumors." (PMID 35757728, 2022). "We found that expression of AHSA1 as well as tumor stage are the independent prognosis predictors for HCC patients." (PMID 36230524, 2022). "The abnormal expression of AHSA1 is related to the infiltration of immune cells, the expression of immune checkpoints, and the expression of various tumor pathway molecules in pan-cancer." (PMID 35757728, 2022). "Both unpaired analysis and paired analysis showed that AHSA1 has higher expression in HCC tumor tissues." (PMID 35757728, 2022). "For further evaluation of the specific effect of AHSA1 on tumor survival, the influence of abnormal AHSA1 expression on disease-specific survival (DSS) of tumor patients was observed." (PMID 35757728, 2022). "Interestingly, in TCGA database, AHSA1 was highly expressed in tumor groups, and LUAD patients with high-expression AHSA1 had poor prognosis." (PMID 37033259, 2023). "Although, the role of AHSA1 in tumor cells is still unrecognized." (PMID 35757728, 2022). "This also indicated the significant involvement of AHSA1 in the progression of tumor." (PMID 35757728, 2022). "According to these findings the AHSA1 may play a certain role in the regulation of tumor microenvironment." (PMID 35757728, 2022). "In addition, N-cadherin was downregulated and E-cadherin was upregulated in tumor tissues of mice injected with HCCLM3-sh-AHSA1-1, suggesting that loss of AHSA1 reduced the EMT of HCC in vivo." (PMID 36230524, 2022). "All our results suggest that miR-338-3p acts as a tumor suppressor in OS cells by targeting AHSA1." (PMID 29618948, 2018). "Therefore, we preliminarily speculated that AHSA1 might promote the tumor progression through regulating the polarization of Th2 and macrophages cells." (PMID 35757728, 2022). "AHSA1, an activator of heat shock protein 90 (HSP90), likely enhances the stability of multiple oncogenic proteins, promoting tumor growth and survival." (PMID 40358702, 2025). "According to this study, based on the TCGA database, AHSA1 was abnormally overexpressed in different types of tumors through unpaired and paired comparisons, but was expressed in low quantities in the KIRC tumor tissues." (PMID 35757728, 2022). "For further confirmation of the value of prognosis of AHSA1 in HCC, the expression of AHSA1 in para-cancer and tumor tissues in the ICGC-LIRI-JP queue were analyzed." (PMID 35757728, 2022). "In addition, CLDN18 also correlated significantly with markers of activated CD8 + T cells such as MPZL1, CSE1L, CD37, AHSA1, CD3D and IL2RB, after adjusting for tumor purity." (PMID 37438735, 2023). "Moreover, overexpression of AHSA1 reversed the inhibitory effect of miR-338-3p overexpression on proliferation, cell cycle, apoptosis, EMT, migration, and invasion of MG63 and Saos2 cells, thereby suggesting that miR-338-3p acts as a tumor suppressor in OS cells by targeting AHSA1." (PMID 29618948, 2018).
cancer (7 papers, 2015 to 2025). A tumor composed of atypical neoplastic, often pleomorphic cells that invade other tissues. "Based on the TCGA database, the Kaplan-Meier curves helped in depicting the association between abnormal expression of AHSA1 and the general pan-cancer survival." (PMID 35757728, 2022). "Therefore, the association between TMB or MSI and AHSA1 expression was observed in 33 commonly known types of cancers." (PMID 35757728, 2022). "A pan-cancer study of AHSA1 expression levels demonstrated that AHSA1 was substantially expressed in LUAD compared to normal tissue." (PMID 37033259, 2023). "The mRNA expression of AHSA1 was evaluated in pan-cancer patients according to the RNA-seq data of 33 types of TCGA tumors." (PMID 35757728, 2022). "Recently, AHSA1 has been found to play an oncogenic role by promoting the proliferation and metastasis of malignant tumors, including osteosarcoma, colorectal adenocarcinoma, and multiple myeloma." (PMID 36230524, 2022). "Combined with clinical follow-up data, the impact of abnormal expression of AHSA1 on the prognosis of cancer patients was analyzed." (PMID 35757728, 2022). "The activator of 90 kDa heat shock protein ATPase homolog 1 (AHSA1) was reported to play a role in the regulation of related cancer-promoting proteins depending on a chain reaction between the central region of HSP90 and the AHSA1 N-terminal domain." (PMID 36230524, 2022). "Although previous studies have suggested the prognostic importance and expression level of AHSA1 in various types of cancers, little is known if the abnormal expression of AHSA1 have an influence on immune cell infiltration." (PMID 35757728, 2022). "In addition, FNDC4 was negatively correlated with AFP, a tumor marker of HCC, and other cancer-related genes such as AHSA1, GDF1, GPC3 and MDK." (PMID 38021165, 2023). "In fact, the oral ERK1/2 phosphorylation inhibitor MK-8353, which has a similar mechanism to the ERK1/2 phosphorylation inhibitor SCH772984, has shown some promising results in clinical studies of cancer patients, implies a new choice for patients with AHSA1 overexpression." (PMID 36230524, 2022). "Intriguingly, AHSA1 selectively mediates the recruitment of client proteins to Hsp90 system as an adaptor co-chaperone suggesting the therapeutic potential of targeting AHSA1 in cancer treatment." (PMID 34991674, 2022). "Considering that AHSA1 is an ATPase activator of HSP90AA1, we analyzed the expression of HSP90AA1 in pan-cancer." (PMID 35757728, 2022). "Activator of HSP90 ATPase activity 1(AHSA1) was reported to be involved in regulating the maturation, stability, and degradation of related cancer-promoting proteins." (PMID 36230524, 2022). "AHSA1 as a chaperone of HSP90 promotes the maturation, stability, and degradation of related cancer-promoting proteins." (PMID 36230524, 2022). "However, current studies are limited to a few types of cancers, and the role of AHSA1 in various types of tumors is still not understood completely." (PMID 35757728, 2022).
AHSA1 also shares sentences with these, for which no sentence is quoted: Alzheimer disease (1 paper); cholangiocarcinoma (1); esophageal carcinoma (1); Fever (1); hypoparathyroidism (1); infection (1); lung carcinoma (1); Pan (1); pancreatic cancer (1); renal cell carcinoma (1); renal dysplasia (1); viral infection (1).